PFKM (phosphofructokinase, muscle)
Diseases named in the same sentence as PFKM in open-access papers (continued):
Sharing a sentence is not in itself a finding about the gene and the disease.
PFKM also shares sentences with these, for which no sentence is quoted: melanoma (4 papers); bladder cancer (3); lung carcinoma (3); brain tumor (2); endometrial carcinoma (2); head and neck carcinoma (2); malaria (2); metastatic tumors (2); schizophrenia (2); T-cell acute leukemia (2); T-cell leukemia (2); thyroid cancer (2); triple-negative breast carcinoma (2); adenocarcinoma (1); atherosclerosis (1); autoimmune disease (1); benign tumors (1); brain glioma (1); Cerebral ischemia (1); colon cancer (1); cystic fibrosis (1); diastolic heart failure (1); distal renal tubular acidosis (1); gastric cancer (1); gouty arthritis (1); head and neck squamous cell carcinoma (1); hemangioma (1); Huntington disease (1); Hyperglycemia (1); Hypertension (1).
A further 28 diseases each share a sentence with PFKM in 1 paper.